HORMAD1 (HORMA domain containing 1)
Diseases named in the same sentence as HORMAD1 in open-access papers (continued):
Sharing a sentence is not in itself a finding about the gene and the disease.
tumor (16 papers, 2014 to 2024). "In many different tumor types, HORMAD1 expression correlates with increased mutation burden and chromosomal scarring." (PMID 37838177, 2023). "Using the same conditions on 99 tumor sections of mixed types, we verified that most triple-negative tumors (34 out of 40, 85%) expressed HORMAD1 and/or CT83, and this activation is specific to the triple-negative subtype (p-value < 10−4)." (PMID 38467851, 2024). "Multivariate analysis using a Cox proportional hazards model assessed the predictive value for MFS and the parameters with a P‐value < 0.1 in univariate analysis, including LN status, macroscopic tumor size and HORMAD1 mRNA expression." (PMID 36852691, 2023). "The same group recently reported that tumor cells expressing HORMAD1 have specific vulnerabilities related to their ability to repair DNA damage or replicate through damaged DNA." (PMID 36852691, 2023). "By combining HORMAD1 status and macroscopic tumor size status, we identified four separate prognostic groups with significantly different MFS curves (P = 0.0056)." (PMID 36852691, 2023). "The prognostic significance of LN status (P = 0.0001), macroscopic tumor size (P = 0.029) and HORMAD1 mRNA expression persisted in multivariate analysis." (PMID 36852691, 2023). "We observed an increase in signal in sgHORMAD1 cells than sgCTRL at baseline, suggesting HORMAD1 protects tumor cells from endogenous DNA damage." (PMID 37838177, 2023). "The patients with the poorest prognosis had low HORMAD1 expression and large tumor size (> 25 mn), while those with the best prognosis had high HORMAD1 expression and small tumor size (≤ 25 mn)." (PMID 36852691, 2023). "Specifically, we and others have found that HORMAD1 is frequently expressed in a wide variety of neoplasms including lung, breast, and ovarian cancers." (PMID 37838177, 2023). "In this study, our results revealed that HORMAD1 promotes tumor growth and metastasis in vivo using xenograft models and models of liver and lung metastasis." (PMID 35347116, 2022). "Ectopic expression of HORMAD1 enhances tumor formations in two of these models, and significantly reduces sensitivity to Rucaparib in the HCC1954 model." (PMID 30046392, 2018). "Upon tumor establishment, mice bearing either HORMAD1-overexpressing tumors or YFP-expressing tumors were randomized and treated with Rucaparib (10 mg/kg) or the vehicle phosphate-buffered saline (PBS)." (PMID 30046392, 2018). "We found that HORMAD1 overexpression significantly increased tumor growth in HCC1954 xenograft tumors compared to YFP-expressing controls." (PMID 30046392, 2018). "While subjected to Rucaparib treatment, overexpression of HORMAD1 in the HCC1954 model reduced tumor sensitivity to Rucaparib treatment, which is consistent with our analyses of cell line data." (PMID 30046392, 2018). "Therefore, to determine HORMAD1 protein localization and expression patterns in cSCC, we performed immunohistochemical analysis of 18 cSCC tumor biopsy samples isolated from patients." (PMID 37371097, 2023). "Here, we report that HORMAD1 protects LUAD tumor cells from genomic instability." (PMID 37838177, 2023). "If potent and specific drug-like inhibitors of TLS polymerases can be further developed they may represent a novel therapeutic strategy for a majority subgroup of TNBCs and potentially other tumour sites with clearly identifiable HORMAD1 expression." (PMID 35768547, 2022). "To explore whether HORMAD1 promotes tumor metastasis in vivo, we injected the indicated cells into the tail vein or the subcapsular region of the nude mice to develop lung and liver metastasis models, respectively." (PMID 35347116, 2022). "Since HORMAD1 expression does not increase mutation load in cultured cells in vitro, it is difficult to test this idea using mouse tumor cells in immune-competent mouse models." (PMID 32647118, 2020).
tumor (continued). "This was reinforced by our finding that tumor samples with high HORMAD1 expression have significantly higher levels of genomic instability (as measured by genomic copy number variation) than tumors with low expression of HORMAD1 (p = 5.61e-6)." (PMID 30333500, 2018). "This indicates that HORMAD1 activity is broadly upregulated in tumor cells." (PMID 30333500, 2018). "Taken together, our data suggest that epigenetic activation of HORMAD1 by hypomethylation in BLBC may endow reduced sensitivity to Rucaparib treatment in some tumor models." (PMID 30046392, 2018). "To further test the association of HORMAD1 overexpression with tumor response to Rucaparib treatment in vivo, we generated several xenograft mouse models using BLBC cell lines engineered to ectopically overexpress HORMAD1 and assessed the tumors’ responses to Rucaparib treatment." (PMID 30046392, 2018). "Furthermore, depletion of HORMAD1 attenuates in vivo tumor growth in lung cancer xenografts." (PMID 37838177, 2023). "In the alternative possibility, the expression of HORMAD1 and CT83 occurs after transformation, equipping basal tumor cells with a selective advantage." (PMID 38467851, 2024). "Increasing the resolution of our analysis, we then used full-length scRNA-seq of triple-negative tumors and again identified robust expression of HORMAD1 and CT83 in tumor cells." (PMID 38467851, 2024). "Of the four analyzed triple-negative breast tumors we found several HORMAD1 (in 3/4 tumors) and CT83 (in 4/4 tumors) positive cells: they fall primarily into the tumor cell cluster." (PMID 38467851, 2024). "To explore the protumorigenic role of HORMAD1 in vivo, we subcutaneously injected the H157-HORMAD1 and H650-HORMAD1 KO cells and the corresponding control cells into the armpit of BALB/c-nude mice to evaluate the effect of HORMAD1 on tumor growth." (PMID 35347116, 2022). "Previously, we found that HORMAD1, a protein normally only expressed in meiotic cells, is bi-modally expressed in TNBC, with 60% of tumours showing high-level expression, while the other 40% showing little to no expression." (PMID 35768547, 2022). "In conclusion, our data identifies a number of HORMAD1-induced genetic dependencies, which might be selectively targeted with small molecules in a group of high unmet need malignancies with readily identifiable tumour restricted expression of the meiotic protein HORMAD1." (PMID 35768547, 2022). "Quantitative polymerase chain reaction (qPCR) analysis revealed higher levels of SOX11, FHAD1, HORMAD1 and TFAP2B expression in DCIS‐SOX11 than in DCIS‐LacZ tumours." (PMID 28707729, 2017). "In the positive tumors, staining for HORMAD1 was predominantly nuclear, present in most or all tumor cells, and seemed absent from non-tumor cells of the microenvironment." (PMID 38467851, 2024). "To further elucidate the molecular mechanisms of HORMAD1 in tumor cells, we performed HORMAD1 immunoprecipitations followed by nano-HPLC mass spectrometry (MS) to identify endogenous HORMAD1 complexes in two LUAD cell lines, A549 and H1395, which express robust amounts of HORMAD1." (PMID 37838177, 2023). "A body of emerging evidence has revealed that meiotic chromosome regulator genes, including REC8, SMC1β, RAD21L1, TEX19, HORMAD1, and SYCP3, are inappropriately activated to modulate chromosome maintenance and segregation in tumor development, maintenance, and spread." (PMID 34150762, 2021). "In the BT20 model which bears a BRCA2 mutation, Rucaparib treatment decreased tumor growth as expected, but HORMAD1 overexpression did not affect baseline tumor growth or response to Rucaparib." (PMID 30046392, 2018). "This tumor panel does not have associated PAM50 data, and thus it cannot be used to evaluate differential HORMAD1 expression in different PAM50 subtypes." (PMID 30046392, 2018). "HORMAD1 status was not related to macroscopic tumor size and LN status in this series." (PMID 36852691, 2023).
tumor (continued). "Interestingly, one of the four tumors shows two subclusters of tumor cells: one subcluster is positive for HORMAD1 yet the second is not, revealing that intra-tumoral heterogeneity may exist in some samples." (PMID 38467851, 2024). "On the other hand, HORMAD1 overexpression only lead to moderately increased tumor growth in the HCC1806 xenograft model, while BT20 xenograft growth is not affected by HORMAD1 protein level at all." (PMID 30046392, 2018). "However, to date, no studies have revealed the role of HORMAD1 as a CTA in EMT and tumor metastasis." (PMID 35347116, 2022).
HORMAD1 also shares sentences with these, for which no sentence is quoted: osteosarcoma (2 papers); Azoospermia (1); cyst (1); gastric cancer (1); hepatocellular carcinoma (1); lung squamous cell carcinoma (1); type 2 diabetes (1).